SERBP1 (SERPINE1 mRNA binding protein 1)
Diseases named in the same sentence as SERBP1 in open-access papers (continued):
Sharing a sentence is not in itself a finding about the gene and the disease.
cancer (15 papers, 2013 to 2026). A tumor composed of atypical neoplastic, often pleomorphic cells that invade other tissues. "Lastly, the role of SERBP1 RNA-binding protein in pathways associated to cancer development was reported in glioblastoma." (PMID 35326503, 2022). "Despite its regulatory importance and implication in cancer development, the molecular basis of SERBP1 RNA recognition remains poorly understood." (PMID 41846982, 2026). "SERBP1 is a conserved RNA-binding protein involved in various cellular physiological processes, including cell division, DNA damage response, and cancer development." (PMID 39717265, 2024). "All these results were considered together with the promoting effect of SERBP1 overexpression on cell apoptosis, especially in cancer cells." (PMID 36213507, 2022). "Recently, SERBP1 was described to co-sediment with the 40S ribosomal subunit in actively translating ribosomes, as polysomes, in normal and cancer cells, opening a new view on its involvement in tumor progression." (PMID 35326503, 2022). "Our analysis of SERBP1 AS genes showed that SERBP1 regulated cancer cells probably through pyruvate and fatty acid metabolic processes, consistent with previous studies on cancer cells." (PMID 36213507, 2022). "We identified hundreds of DEGs and RASGs using RNA-seq, showing that SERBP1 has many functions, especially in cancer." (PMID 36213507, 2022). "Using K-M plotter tool, we found that higher expression levels of SERBP1 affected the prognosis results of several cancers." (PMID 36213507, 2022). "We first investigated the expression pattern of SERBP1 in all the cancer types from the cancer genome atlas (TCGA) database using GEPIA2 web server." (PMID 36213507, 2022). "To understand how SERBP1 contributes to cancer-relevant phenotypes, we performed an RNA-Seq analysis in control vs. SERBP1 knockdown U251 cells." (PMID 32762776, 2020). "SERBP1 is the first example of an RNA-binding protein functioning as a central regulator of cancer metabolism and indirect modulator of epigenetic regulation in GBM." (PMID 32762776, 2020). "We conducted several assays to determine if high expression of SERBP1 is required to maintain cancer-relevant phenotypes." (PMID 32762776, 2020). "Due to its broad impact on cancer-relevant processes and pathways, SERBP1 emerges as an important oncogenic factor and potential therapeutic target." (PMID 32762776, 2020). "Our findings unveil novel roles of vIL-6 and SERBP1 deacetylation in regulating ferroptosis and KSHV-induced cellular transformation, and establish the vIL-6-SIRT3-SERBP1-ferroptosis pathways as a potential new therapeutic target for KSHV-associated cancers." (PMID 38470932, 2024). "In addition, various human cancer cell lines that develop resistance to cisplatin also expressed increased level of SERBP1." (PMID 38470932, 2024). "We proved that the overexpression of SERBP1 can promote the apoptosis of HeLa cells, and we propose that it may also have the same influence in other cancer cells." (PMID 36213507, 2022). "We predict that SERBP1 may regulate cancer cells through pyruvate and fatty acid metabolic processes." (PMID 36213507, 2022). "In this study, we found that overexpression of SERBP1 influenced cancer cell proliferation and apoptosis through DEGs by a variety of mechanisms, indicating SERBP1 may participate in the metabolism of cancer cells." (PMID 36213507, 2022). "Therefore, according to the information above, we conclude that SERBP1 has a strong relationship with cancer cells." (PMID 36213507, 2022). "We then analyzed the prognosis effects according to SERBP1 expression levels in cancers." (PMID 36213507, 2022). "Regulation of these mechanisms by SERBP1 may elucidate the pathways by which aggressive cancers thrive." (PMID 32762776, 2020). "Genomic analysis indicated that SERBP1 is a critical player in cancer metabolism." (PMID 32762776, 2020).
cancer (continued). "We predicted that the overexpression of SERBP1 may modulate the apoptosis levels of cancer cells." (PMID 36213507, 2022). "In the case of SERBP1, its blockage could hit cancer metabolism and epigenetic regulation." (PMID 32762776, 2020). "Our findings unveil a novel role of SERBP1 in KSHV-induced cellular transformation and identify a potential therapeutic target for KSHV-induced cancers." (PMID 38470932, 2024). "Furthermore, we know that the overexpression of SERBP1 could promote the apoptosis of cancer cells." (PMID 36213507, 2022). "SUMOylation of SERBP1 has been suggested as a factor in the development of GBM, as aberrations in SUMOylation pathways can lead to the development of cancer." (PMID 34631798, 2021). "SERBP1 is a member of the RG/RGG family of RNA-binding proteins, known for their involvement in neurological and neuromuscular diseases and cancer." (PMID 32762776, 2020).
neurological disorders (5 papers, 2020 to 2025). "Overall, our results indicate that besides its role in GBM development, SERBP1 might be implicated in brain function and neurological disorders." (PMID 32762776, 2020). "SERBP1 has not been studied in the context of the nervous system, and its contribution to neurodegenerative diseases and neurological disorders remains to be investigated." (PMID 39937575, 2025).
infection (4 papers, 2020 to 2024). The state of being infected such as from the introduction of a foreign agent such as serum, vaccine, antigenic substance or organism. "SERBP1 is known to shuttle between the cytoplasm and the nucleus and certainly in lytic infection has been observed to be located in both locations." (PMID 36504797, 2022). "We selected the highly aggressive GSC line 3565 and prepared a stable line containing a tet-inducible SERBP1 shRNA via lentiviral infection." (PMID 32762776, 2020). "We generated, via lentiviral infection, a U343 line that overexpresses SERBP1 (SERBP1 OE)." (PMID 32762776, 2020). "To explore the function of CTTN, SERBP1, and STMN1 in infection of NiV, we conducted pseudoviral infection experiments." (PMID 38612921, 2024). "Monitoring the AS profile of the negative control ASE (SERBP1) showed no change throughout the infection, hence showing that the modulation of AS is specific and timely regulated." (PMID 35489070, 2022). "We suspect that the reason why SERBP1 and STMN1 do not significantly affect NiVpv infection is due to the limitation that the pseudovirus we used can only carry out one round of infection and cannot replicate." (PMID 38612921, 2024).
animal diseases (1 paper, 2025). "In the future, it is necessary to carry out research on SERBP1 in agricultural animal diseases (such as avian leukosis and bovine luteal dysfunction) to provide new targets for the prevention and control of livestock and poultry diseases." (PMID 41227349, 2025). "With the advancement of research techniques, the molecular mechanism of SERBP1 will be further clarified, and its application potential in disease diagnosis and treatment will be gradually realized, providing important support for human health and the prevention and control of animal diseases." (PMID 41227349, 2025).
neurodegenerative disease (1 paper, 2025). A disorder of the central nervous system characterized by gradual and progressive loss of neural tissue and neurologic function. "Several RBPs containing intrinsically disordered regions, like SERBP1, have been shown to display alterations in LLPS in neurodegenerative diseases." (PMID 39937575, 2025).
SERBP1 also shares sentences with these, for which no sentence is quoted: atherosclerosis (2 papers); cervical squamous cell carcinoma (2); leukemia (2); lung adenocarcinoma (2); pancreatic adenocarcinoma (2); acute lymphoblastic leukemia (1); Arrhythmia (1); astrocytoma (1); bladder urothelial carcinoma (1); Cardiovascular Disease (1); Cerebrovascular Disease (1); cholangiocarcinoma (1); colon adenocarcinoma (1); colorectal cancer (1); dengue virus infection (1); diffuse large B-cell lymphoma (1); dyslipidemia (1); epileptic seizures (1); high blood pressure (1); lymphoid neoplasm (1); malignant brain tumor (1); non-small cell lung carcinoma (1); oral cancer (1); rectal cancer (1); rectum adenocarcinoma (1); rectum tumors (1); Rett syndrome (1); sarcoma (1); squamous lung-cell carcinoma (1); steatosis (1).
A further 4 diseases each share a sentence with SERBP1 in 1 paper.